ENSG00000260035 (novel transcript)
Gene: Long non-coding RNA gene on chromosome 15 (45,200,325 to 45,200,632, reverse strand). Ensembl gene ENSG00000260035.
Gene Ontology:
Molecular function: triplet codon-amino acid adaptor activity
Biological process: translation